AGR2 (anterior gradient 2, protein disulphide isomerase family member)
Diseases named in the same sentence as AGR2 in open-access papers (continued):
Sharing a sentence is not in itself a finding about the gene and the disease.
breast cancer (continued). "Significant difference of AGR2 expression rate in different molecular subtypes of breast cancer." (PMID 37197416, 2023). "Moreover, we aimed to examine the association of the combination of AGR2 and FOXA1 with the prognosis of breast cancer." (PMID 37568077, 2023). "The correlation between AGR2 expression and ER positive rate of breast cancer cell lines and the ability of estradiol to induce its expression suggests that AGR2 may mediate the normal physiology and estrogen effect of breast cancer." (PMID 37197416, 2023). "The recruitment of the hnRNPL-LINC02273 complex to the promoter of AGR2 (anterior gradient 2, a disulfide isomerase associated with decreased breast cancer survival) increases local H3K4me3 and H3K27 acetylation, thereby epigenetically upregulating AGR2 and promoting BC metastasis." (PMID 35865634, 2022). "The human homologue named AGR2 was first identified in the EsR-positive breast cancer cell lines." (PMID 35965326, 2022). "AGR2 could serve as a biomarker for the prognosis of metastasis and chemotherapeutic response in breast cancer, lung cancer, gastric cancer, esophageal squamous cell carcinoma." (PMID 35055132, 2022). "On the other hand, high SOX2 and AGR2 expression with high serum level of serum AGR2 may predict a subset of breast cancer patients that are less likely to show adequate tumor growth control or recurrence following tamoxifen therapy." (PMID 34567804, 2021). "The relation between Sox2 and AGR2 expression and breast cancer has been broadly studied." (PMID 34567804, 2021). "In human, AGR2 has been first identified in oestrogen-receptor-positive breast cancer cells." (PMID 34452625, 2021). "In this study, we found AGR2 was up-regulated in doxorubicin-resistant breast cancer cells." (PMID 30665445, 2019). "Similarly, the knockdown of AGR2 in the human breast cancer cell lines ZR-75-1 and T47D using siRNA resulted in the downregulation of survivin (BIRC5), c-Myc and p-Src proteins." (PMID 31247903, 2019). "All these suggest that manipulating expression of AGR2 might counteract drug-resistance in breast cancer, especially in those who with high level of AGR2." (PMID 30665445, 2019). "Moreover, the knockdown of AGR2 in the breast cancer cell lines T47D and MCF7 strongly induced p27 and p21 expressions." (PMID 31247903, 2019). "Others reported that level of AGR2 positively correlated with expression of ER in breast cancer." (PMID 30665445, 2019). "In breast cancer, increased AGR2 had an unfavorable impact on survival." (PMID 31856843, 2019). "AGR2 was shown to induce expression of cyclin D1 in breast cancer cells." (PMID 30665445, 2019). "We found hnRNPL enhanced AGR2 transcription in breast cancer cells." (PMID 31856843, 2019). "AGR2 mediated doxorubicin-sensitivity of breast cancer cells both in vitro and in vivo." (PMID 30665445, 2019). "AGR2 also mediates resistance to hormone therapy in breast cancer." (PMID 30665445, 2019). "Level of miR-194-5p also negatively correlated with level of AGR2 in breast cancer cell lines." (PMID 30665445, 2019). "Expression of AGR2 was up-regulated in doxorubicin-resistant breast cancer cells." (PMID 30665445, 2019). "AGR2 was also implied to mediate doxorubicin resistance in breast cancer cells." (PMID 30665445, 2019). "Taken together, these data strongly support that high LINC02273 expression correlates with poor RFS in breast cancer, and downstream increase of AGR2 expression in the hnRNPL-LINC02273 axis may promotes breast cancer metastasis." (PMID 31856843, 2019). "In addition, levels of AGR2 negatively correlated with levels of miR-135b-5p in clinical breast cancer tissue samples." (PMID 30665445, 2019). "Thus, in addition to ER-dependant mechanism, we identified that miR-135b-5p is another regulator of AGR2 in breast cancer." (PMID 30665445, 2019).
breast cancer (continued). "The opposing associations of AGR2 and ESR1 expression with DSS could reflect the role of AGR2 in hormone therapy- resistant ER+ breast cancer: ER+ breast cancers may develop resistance by overexpressing AGR2." (PMID 29796176, 2018). "A combined strategy to block AGR2 expression or function in combination with anti-estrogenic hormonal therapy may be a novel strategy for the treatment of ER+ breast cancers." (PMID 29796176, 2018). "The TCGA breast cancer cohort was not useful for a validation of the AGR2 survival association due to inadequately short follow-up time of the cohort." (PMID 29796176, 2018). "For example, AGR2 is overexpressed and secreted by both bladder and breast cancer cells." (PMID 29796176, 2018). "A possible explanation would be that AGR2 overexpression might increase breast cancer cells’ proliferative and invasive capacity." (PMID 29138453, 2017). "We also analysed the relationship between AGR2 and clinicopathological features of breast cancer." (PMID 29138453, 2017). "Further functional studies are needed to clarify AGR2’s role in breast cancer." (PMID 29138453, 2017). "Furthermore, in breast cancer, high expression of AGR2 trends to correlate with ER positivity, PgR positivity and low histological grade." (PMID 29138453, 2017). "Therefore, we report that AGR2 is a key modulator involved in IGF-1-induced breast cancer development." (PMID 25956506, 2015). "Interestingly, tamoxifen enhanced AGR2 expression, and AGR2 was found to be a predictor of poorer prognosis in tamoxifen-treated breast cancers." (PMID 26445321, 2015). "Thus our data clearly show the potential usability of AGR3 and AGR2 as biomarkers for blood-based early detection of human breast cancer." (PMID 25875093, 2015). "Furthermore, our results are in line with recent findings for the homologous protein AGR2 that is now discussed as being a prognostic factor of an adverse prognosis in breast cancer." (PMID 25875093, 2015). "Treatment of breast cancer patients with Letrazole resulted in decreased AGR2 transcription." (PMID 26445321, 2015). "AGR2 overexpression in breast cancer cells promotes cell migration and malignant transformation." (PMID 25956506, 2015). "Moreover, we demonstrate that both proteins AGR3 and AGR2 are detectable by ELISA technique at significantly elevated concentrations in sera from breast cancer patients compared with age-matched serum samples from healthy women." (PMID 25875093, 2015). "Hence, our findings clearly show for the first time the potential usability of AGR3 and AGR2 as biomarkers for non-invasive early detection of human breast cancer." (PMID 25875093, 2015). "In addition, rat mammary tumor cells overexpressing AGR2 showed increased metastatic potential when injected orthotopically in syngeneic rats." (PMID 25367337, 2014). "Although emerging evidence indicates that AGR2 is associated with poor prognosis, its function and impact on cancer-relevant pathways have not been elucidated in breast cancer." (PMID 20525379, 2010). "Given the high level of biologic relevance of p-Src, survivin, and c-Myc in cancer, modulation of these key players after silencing AGR2 suggests that AGR2 may be the key in other cancers, beyond breast cancer." (PMID 20525379, 2010). "Because cyclin D1 is induced with an exogenous source of AGR2 and reduced with an anti-AGR2 Ab, and AGR2 is detected in the supernatant of breast cancer cell lines, it suggests that AGR2 may have an extracellular mechanism of action." (PMID 20525379, 2010). "It is to be hoped that knowledge of expression of AGR2 may, in the future, help to inform treatment decisions for patients with ERα-positive breast cancers in the adjuvant or extended adjuvant settings." (PMID 16598187, 2006). "Therefore, we investigated whether high or low H6PD and AGR2 protein expression in breast cancer tissue correlates with the upregulation of pathways that are critical for breast cancer progression." (PMID 40281598, 2025).
breast cancer (continued). "Additionally, studies have indicated that AGR2 could serve as a predictor of cancer invasion and the effectiveness of immunotherapy in pancreatic and breast cancers." (PMID 39062458, 2024). "For the prognostic roles of AGR2 in breast cancer, the findings were also inconsistent with positive and negative associations, suggesting the role of AGR2 may also be affected by other factors." (PMID 37568077, 2023). "In conclusion, AGR2 has a unique primary protein structure, including secretory signal, endoplasmic reticulum retention sequence, as well as protein disulfide isomerase active site and a variety of protein binding sequences, which endows AGR2 with diverse roles in breast cancer cells." (PMID 37197416, 2023). "Therefore, it is necessary to carry out more retrospective and prospective studies to clarify the molecular function and clinical role of AGR2, taking into account the heterogeneity and complexity of breast cancer molecules and the impact of breast cancer chemotherapy." (PMID 37197416, 2023). "Interestingly, the expression of AGR2 in breast cancer cells required the transcription factor FOXA1, and our findings suggested that only decreasing the expression of FOXA1 could not entirely prevent the corresponding signal pathway." (PMID 37568077, 2023). "Therefore, targeting ER and Twist1 pathway at the same time may be enough to inhibit AGR2 and improve the survival rate of breast cancer patients." (PMID 37197416, 2023). "However, miR-135b-5p was down-regulated in doxorubicin-resistant breast cancer cells as well as during treatment with doxorubicin, which might be a probable reason for over-expression of AGR2." (PMID 30665445, 2019). "Importantly, AGR2 was implied to mediate drug resistance in breast cancer." (PMID 30665445, 2019). "However, miRNAs-mediated regulation of AGR2 is still unclear in breast cancer." (PMID 30665445, 2019). "High AGR2 expression could be observed in ER-negative breast cancers, while some ER-positive cases showed low levels of AGR2 suggesting that mechanisms other than ER might control expression of AGR2 in breast cancer." (PMID 30665445, 2019). "As therapy inefficacy and subsequent metastases drive breast cancer mortality, further elucidation of both intracellular and extracellular AGR2 biology and its ability to confer hormone therapy resistance may lead to improved understanding of breast cancer mortality." (PMID 29796176, 2018). "Furthermore, AGR2 has been shown to promote cell cycle progression via induction of cell cycle proteins such as cyclin D1, and extracellular AGR2 knockdown using anti-AGR2 antibodies in three ER+ breast cancer cell lines significantly reduces cyclin D1 protein levels and cell growth." (PMID 29796176, 2018). "Finally, the discussion above highlights the significant body of laboratory research that has established the biological plausibility for AGR2 expression as a prognostic biomarker and potential therapeutic target in breast cancer, lending credence to our findings." (PMID 29796176, 2018). "However, in breast cancer patients, AGR2’s high expression was predictive of poor outcomes." (PMID 29138453, 2017). "Gene enrichment analysis was performed to investigate the pathway enrichment in breast cancer tissue in relation to H6PD and AGR2 protein expression." (PMID 40281598, 2025). "Gene set enrichment analysis revealed multiple overlapping pathways enriched in breast cancer tissues with relatively high H6PD and AGR2 expression." (PMID 40281598, 2025). "Due to the reported role of AGR2 in breast cancer and our observations of the impact of H6PD on breast cancer cell properties, we selected AGR2 from the pool of potential interactors for further investigations." (PMID 40281598, 2025). "For this purpose, gene set enrichment analysis was performed to identify enriched pathways in breast cancer tissue based on relatively high and low H6PD and AGR2 protein expression." (PMID 40281598, 2025).
breast cancer (continued). "Both AGR2 and H6PD have been proposed to play a role in breast cancer progression, with elevated levels of these proteins being associated with increased breast cancer cell proliferation and migration." (PMID 40281598, 2025). "Glycolysis, fatty acid metabolism, hypoxia, angiogenesis, and epithelial to mesenchymal transition pathways were enriched in breast cancer tissue exhibiting relatively high H6PD and AGR2 expression." (PMID 40281598, 2025). "AGR2 was screened from MCF7, an estrogen receptor positive breast cancer cell line, and its transcription is responsive to estrogen at the molecular level." (PMID 38390317, 2024). "FOXA1, observed in breast cancer and HCC, serves as a transcriptional activator of liver-specific transcripts, stimulating AGR2 expression and fostering HCC recurrence and metastasis." (PMID 39062458, 2024). "Considering that there were interplays between them depending on ER status, we aimed to assess the statistical interaction between AGR2 and FOXA1 on breast cancer prognosis and examine the prognostic role of the combination of them by ER status." (PMID 37568077, 2023). "Another implication is that four of the genes identified in this study—AGR2, AGR3, TFF3, and SCUBE2—have protein products that are secreted in the blood by breast cancer." (PMID 36836779, 2023). "In both univariate and multivariate analyses, statistical interaction between AGR2 and FOXA1 on the PFS was significant (all P < 0.05) based on every cutoff point for ER-positive breast cancer." (PMID 37568077, 2023). "AGR2 and FOXA1 expression in tumor tissues were evaluated with tissue microarrays by immunohistochemistry in 915 breast cancer patients with follow up data." (PMID 37568077, 2023). "Circular RNA CircPVT1 mediates AGR2-HIF-1α axis through MiR-29a-3p, promoting the growth, invasion, migration and inhibiting apoptosis of breast cancer cells." (PMID 37197416, 2023). "AGR2 and AGR3 expression are coupled in EsR positive breast cancer and the combination of AGR2 and AGR3 as biomarkers resulted in increased sensitivity and specificity thus suggesting that they can be used as a prognostic factor." (PMID 35965326, 2022). "Five genes demonstrated significantly higher expression in breast cancer bone metastasis (BCBM): TFF1, TFF3, AGR2, NAT1, and CR1P1." (PMID 35804819, 2022). "Anterior Gradient Homolog 2 (AGR2) is a member of protein disulfide isomerase (PDI) family, which is overexpressed in ESCC, lung cancer, breast cancer and other cancer." (PMID 35962061, 2022). "All patients were primarily subjected to serum AGR2 levelling by ELISA and their breast cancer tissue immunostained for SOX2 and AGR2." (PMID 34567804, 2021). "Antibodies against AGR2 and LYPD3 have been found to be effective to suppress growth of TAM-R breast cancer cells in mice." (PMID 34604071, 2021). "AGR2 and AGR3 are co-expressed in human breast cancer, while the expression of AGR2 is exclusive to prostate cancer." (PMID 34452625, 2021). "Human anterior gradient 2 (AGR2), a member of the protein disulfide isomerase (PDI) family, is firstly identified as differentially expressed in estrogen receptor-positive breast cancer cells." (PMID 30647455, 2019). "Consistently, the knockdown of AGR2 in the MCF7 and T47D breast cancer cell lines reduced the fulvestrant treatment resistance in both cell lines, whereas the overexpression of AGR2 in the MCF7 cells increased cell survival under the fulvestrant treatment." (PMID 31247903, 2019). "Combination of AGR2 and LINC02273 was an independent prognostic factor for predicting breast cancer patient survival." (PMID 31856843, 2019). "To further investigate the pathological significance of hnRNPL-LINC02273 axis in breast cancer progression, we analyzed the expression levels of hnRNPL, LINC02273 and AGR2 in primary samples from 606 invasive breast cancer patients." (PMID 31856843, 2019).
breast cancer (continued). "It is therefore plausible that AGR2 is involved in the UPR to resolve endoplasmic reticulum stress, and that breast cancer cells can utilize the homeostatic effects of AGR2 to overcome their own pathologically elevated need for protein synthesis and secretion." (PMID 29796176, 2018). "Simultaneous suppression of AGR2 and ESR1 activity represents a potentially promising concept to be further investigated for breast cancer." (PMID 29796176, 2018). "A third retrospective study of AGR2 as a predictor of disease-free survival reports a significant association of decreased survival and increased tumor AGR2 mRNA expression using qRT-PCR among 78 women with tamoxifen-treated ER+ breast cancer but without adjustment for potential confounders." (PMID 29796176, 2018). "Thus, we speculate that the mechanism for AGR2 overexpression predicting breast cancer’s poor prognosis could be: AGR2 expression was induced in an ER- or HER-dependent manner at the early stage of tumorigenesis, which led to treatment resistance and metastasis." (PMID 29138453, 2017). "In the present study, AGR2 and AGR3 were identified for the first time as putative serum protein biomarkers in breast cancer." (PMID 25875093, 2015). "AGR3 protein was originally identified as breast cancer membrane protein 11 (BCMP11), following a proteomic screen of membrane proteins in breast cancer cell lines, and was later named AGR3 due to the high degree of sequence homology with AGR2." (PMID 23245351, 2012). "TFF1, AGR2 and SBEM were expressed to a varying degree in all breast cancer cell lines, but also in other malignancies." (PMID 21816090, 2011). "To verify the impact of AGR2 on the extracellular milieu of human breast cancer cells, we transfected both invasive MDA-MB-231 and non-invasive MCF7 cells with an expression vector encoding human AGR2." (PMID 38822246, 2024). "AGR2 was found by comparing the protein differences between ER positive and negative breast cancer cells." (PMID 37197416, 2023). "AGR2 was only expressed in estrogen receptor positive breast cancer cell lines, but not in estrogen receptor negative breast cancer cell lines, which attracted great attention when it was found." (PMID 37197416, 2023). "Extracellular AGR2 and ER-α can interact to induce the expression of IGF-1, thereby promoting the proliferation, migration and epithelial-mesenchymal transition process in breast cancer cells and enhancing drug resistance." (PMID 37197416, 2023). "Furthermore, the same research group showed that AGR2 and AGR3 were both co-expressed in estrogen receptor (EsR)-positive breast cancer and can physically interact with LY6/PLAUR Domain Containing 3 (LYPD3 /C4.4a) and extracellular alpha-dystroglycan (DAG-1)." (PMID 35965326, 2022). "Our data show that the expression of POLR3G in breast cancer samples was negatively correlated with that of eight out of ten genes (GATA3; XBP1; AGR2; SIDT1; AR; SPDEF; FOXA1; MLPH) in a list of signature genes most differentially expressed in luminal A compared to basal-like tumors." (PMID 36497214, 2022). "In breast cancer cells, AGR2 over-expression led to the up-regulation of β-DG but not that of α-DG, while the transcript levels of these subunits were unchanged." (PMID 33717413, 2021). "Immunofluorescence analysis showed that the reduced expression of AGR2 effectively down-regulated β-DG protein in the breast cancer cells (AGR2 knock-down did not change co-localization)." (PMID 33717413, 2021). "A similar result was obtained when using a six-gene (AGR2, SLC44A4, TBC1D9, FOXA1, GATA3, and CA12) breast cancer steroid response module (Kruskal-Wallis p = 0.01 across all patients, p = 0.94 in HRDetect-high patients, and p = 0.02 in HRDetect-low/intermediate patients)." (PMID 33568222, 2021). "AGR2, APOE, AQP3, and CD99L2 may be of particular interest for the epithelial differentiating action exerted by circDOCK1-1 in TNBC-mes breast cancer cells." (PMID 34771489, 2021).